SLCO1B1 (solute carrier organic anion transporter family member 1B1)
Diseases named in the same sentence as SLCO1B1 in open-access papers (continued):
Sharing a sentence is not in itself a finding about the gene and the disease.
myopathy (continued). "However, SLCO1B1 may have potential to be clinically important in pravastatin and pitavastatin-induced myopathy." (PMID 25221728, 2014). "Clinical testing and reporting of SLCO1B1 results for statin myopathy risk did not result in poorer ASCVD prevention in a routine primary care setting and may have been associated with physicians avoiding simvastatin prescriptions for patients at genetic risk for SAMS." (PMID 33270123, 2020). "OATP1B1-dependent transport could well be important for the acid (active) form of simvastatin, (and other statins less hydrophobic than pravastatin) as SLCO1B1 variants were recently associated with simvastatin-induced myopathies, implying that OATP1B1 was involved with simvastatin transport." (PMID 26334733, 2015). "In conclusion, no other pharmacokinetic genes (besides SLCO1B1 for simvastatin-induced myopathy) are currently ready for clinical translation." (PMID 25221728, 2014). "Atorvastatin and rosuvastatin are also substrates for SLCO1B1, but the currently available data does not support the clinical translation of SLCO1B1 for prediction of atorvastatin- or rosuvastatin-induced myopathy." (PMID 25221728, 2014). "The currently available literature does not support genes other than SLCO1B1 and SIM clinical outcome, except for possibly CYP2D6 and atorvastatin-induced myopathy." (PMID 25221728, 2014).
cancer (46 papers, 2010 to 2025). A tumor composed of atypical neoplastic, often pleomorphic cells that invade other tissues. "SLCO1B1 is involved in the hepatic uptake of various endogenous compounds, including steroid hormones, and its variants may influence hormone levels and cancer susceptibility." (PMID 40141105, 2025). "It is very interesting that two polymorphisms (rs10454142 PPP1R21 and rs4149056 SLCO1B1) out of eight BC-associated loci are likely drivers of the occurrence of tumors (“likely cancer driver”) (prognostic estimates were obtained by us using the regBase-CAN database)." (PMID 38396861, 2024). "It was found that two SNPs out of eight considered loci, rs10454142 PPP1R21 and rs4149056 SLCO1B1, are the likely drivers of the occurrence of tumors (“likely cancer driver”)." (PMID 38396861, 2024). "SLCO1B1 is important for the disposition of statin drugs and various anti-cancer agents including irinotecan." (PMID 21072184, 2010). "In addition, through pan-cancer analysis, we further demonstrated that SLCO1B1 has a high immune infiltration status in most tumors, especially in B cells, dendritic cells, CD8+ T cells, macrophages, Tregs, and T-cell follicular helper cells." (PMID 37680641, 2023). "Using UALCAN, we further examined protein expression levels of SLCO1B1, SLCO1B3, and SLCO2B1 in normal liver tissues from healthy individuals and cancer liver tissues from HCC patients, based on data from the CPTAC dataset." (PMID 40734706, 2025). "Six of these genes were not expressed or were very weakly expressed (ABCC11, SLC22A6, SLC22A7, SLC22A8, SLC22A9, SLCO1B1), and among the other eight genes, only gene ABCG2 showed significant difference in expression in cancer versus adjacent control tissue." (PMID 33917029, 2021). "In contrast to their widespread overexpression in some cancers, several groups have shown that expression of both SLCO1B3 and SLCO1B1 is decreased in hepatocellular carcinoma at both the mRNA and protein levels." (PMID 32388639, 2020). "We completed a study examining SLCO1B3, SLCO1B1 and SLCO2B1 mRNA expression in 381 primary, independent patient samples representing 21 cancers and normal tissues." (PMID 21625523, 2011). "Using UALCAN, gene transcript expression levels of SLCO1B1, SLCO1B3, and SLCO2B1 were shown to be significantly downregulated in the clinic-pathological characteristics (gender, nodal metastasis status, cancer stages and tumor grade) in HCC patients compared to normal counterparts." (PMID 40734706, 2025). "Likewise, another study comparing expression in normal breast tissue and tumour samples found SLCO1B1 was not highly expressed in these tissues via qPCR, a similar finding to a study involving microarray analysis of human normal breast and cancer tissues." (PMID 32388639, 2020).
tumor (31 papers, 2008 to 2025). "In conclusion, the results of this multi-center prospective study suggest that rs2306283 (GA/AA) of SLCO1B1 in combination with rs1051266 (GG) of SLC19A1 are significantly associated with rapid tumor response to FOLFIRI/mCapeIRI in Chinese mCRC patients." (PMID 24143213, 2013). "However, evidence for an association between SLCO1B1 SNPs and irinotecan-related tumor response and survival in mCRC patients is still unclear." (PMID 24143213, 2013). "It is also important to verify in planning therapy that blood leucocyte or saliva samples were obtained to identify SLCO1B1 alleles because tumour cells may lose these alleles and allele studies based on tumour cells or formalin-fixed paraffin-embedded samples may demonstrate fewer alleles." (PMID 32796505, 2020). "Associations between UGT1A1 (TA)n, UGT1A1 –3156G>A, SLCO1B1*1b 388A>G and ABCC1 IVS11 –48C>T genotypes and drug response (tumour DS, ypT0, OS and RFS) to 5-FU+irinotecan were evaluated for the 35 patients of group 2." (PMID 22045187, 2011). "Expression of SLCO1B1 was detected in all four patient tumours at variable levels." (PMID 34225768, 2021). "The difference in the expression of the five ADME genes (SLC16A1, SLC7A5, SLCO1B1, CYP17A1, and ABCC8) between tumor and normal tissues was significant and was closely correlated with the survival of patients with NSCLC." (PMID 34522968, 2021). "In a recent study we have reported that the levels of SLCO1B1 and SLCO1B3 mRNA are lower in HB tissue than in the adjacent non-tumor liver tissue." (PMID 30909445, 2019). "Expression frequencies were determined for SLCO1B3, SLCO1B1, and SLCO2B1, and the percent of normal or tumor tissues expressing SLCOs are reported." (PMID 21625523, 2011). "As some tumor tissues had similar SLCO expression frequencies as normal tissues, we also ascertained if the magnitude of SLCO expression was different for SLCO1B1, SLCO1B3, and SLCO2B1." (PMID 21625523, 2011). "UALCAN analysis demonstrated significantly reduced SLCO1B1 transcript expression in HCC tissues versus normal liver across all subgroups stratified by gender, nodal metastasis status (N stage), disease stage, and tumor grade." (PMID 40734706, 2025). "To further explore the biological function of SLCO1B1, we first constructed HCC cell lines overexpressing SLCO1B1 and then conducted a series of experiments to explore whether SLCO1B1 could regulate tumor cell proliferation and migration." (PMID 37680641, 2023). "However, from a prognostic perspective, CD5, SLCO1B1, and CD79A have been demonstrated to have protective value in various tumors, whereas ETV5, FZD7, SNX7, and SLC1A7 are involved in tumor progression." (PMID 37680641, 2023). "OATP transporters have been involved in the uptake of vincristine and the expression of both SLCO1B1 and SLCO1B3 have been found lower in HB than in adjacent non-tumor tissue." (PMID 30909445, 2019). "Excluded from the calculation were SLCO1B1 and SLCO1C1, which were rarely expressed in HGSOC tumor tissues and were never observed in benign cysts (data not shown)." (PMID 30131693, 2018).
cardiovascular disease (2 papers, 2019 to 2024). "This study aimed to evaluate the relationship between SLCO1B1 polymorphisms, which can affect ACEI and ARB transport, and gastric mucosal erosion in elderly male Chinese patients with cardiovascular disease who use aspirin." (PMID 31727004, 2019). "Our results show that, although patients carrying SLCO1B1 variants are more likely to be diagnosed with muscle pain and discontinue statin prescriptions, they do not have increased cardiovascular disease risk." (PMID 38674010, 2024).
hematologic malignancies (1 paper, 2023). "A recent study in adult patients with hematologic malignancies receiving high-dose methotrexate suggests that patients with the SLCO1B1 A388G or T521C variants exhibit differential metabolomic profiles that may modulate the risk for methotrexate-induced toxicities." (PMID 36478296, 2023).
SLCO1B1 also shares sentences with these, for which no sentence is quoted: ovarian cancer (5 papers); colorectal cancer (3); leukemia (3); lung carcinoma (3); myositis (3); adenocarcinoma (2); adenoma (2); chronic hepatitis C (2); Crigler-Najjar syndrome (2); Dubin-Johnson syndrome (2); dyslipidaemia (2); encephalitis (2); G6PD deficiency (2); Hepatitis B (2); hepatitis C (2); non-alcoholic steatohepatitis (2); non-small cell lung carcinoma (2); pancreatitis (2); primary biliary cholangitis (2); rheumatoid arthritis (2); thyroid cancer (2); alcoholic liver diseases (1); amenorrhea (1); atransferrinemia (1); benign prostatic hyperplasia (1); brain tumours (1); Burkitt lymphoma (1); Cachexia (1); cholangiocarcinoma (1); chronic headache (1).
A further 50 diseases each share a sentence with SLCO1B1 in 1 paper.